CAB39 (calcium binding protein 39)
Diseases named in the same sentence as CAB39 in open-access papers:
CAB39 is named in the same sentence as 35 diseases in open-access papers, as found by Europe PMC text mining. Sharing a sentence is not in itself a finding about the gene and the disease. The quoted sentences say what the papers report.
glioma (14 papers, 2012 to 2025). A benign or malignant brain and spinal cord tumor that arises from glial cells (astrocytes, oligodendrocytes, ependymal cells). "MiR-451 regulates the proliferation, migration and responsiveness to glucose deprivation of glioma cells by targeting the LKB1/AMPK pathway, and depresses the LKB-1-associated protein CAB39 that promotes glioma cells adapting to metabolic stress." (PMID 32547948, 2020). "For instance, miR-451 is upregulated in glioma compared with control brain tissue; furthermore decreased miR-451 expression was associated to a suppressed tumor cell proliferation via CAB39/AMPK/mTOR pathway in two glioma cell lines." (PMID 31921637, 2019). "Contrary to this finding, miR-451 expression plays different roles in gliomas, as it was associated with the proliferation of cancer cells by suppressing the CAB39/AMPK/mTOR pathway, and increased metastatic potential, which takes place via the activation of the Rac1/cofilin pathway." (PMID 35205289, 2022). "In these glioma cells, miR-451a directly targets CAB39, leading to the inhibition of the PI3K/AKT signaling pathway." (PMID 39129166, 2025). "In glioma cells, miR-451 targets CAB39, a binding partner of LKB1, which in turn phosphorylates and activates AMPK." (PMID 28727756, 2017). "Here, we found a similar phenomenon between CAB39 expression and glioma WHO grades, using immunohistochemistry." (PMID 22179124, 2012). "We conclude that miR-451 represses glioma in vitro and in vivo, likely through targeting CAB39 directly and inhibiting the PI3K/AKT pathway indirectly." (PMID 22179124, 2012). "The downregulation CAB39 by miRNA‐451a inhibits PI3K/Akt pathway in glioma cells." (PMID 30209892, 2018). "Together, these data demonstrated that CAB39 is a target gene of the miR-451 in glioma." (PMID 22179124, 2012). "Indeed, 53/53 high grade gliomas exhibited detectable levels of CAB39, while 3/22 low grade gliomas the protein was at undetectable levels (p<0.05)." (PMID 22179124, 2012). "CAB39 was expressed in gliomas and its total positive rate was 96% (72/75)." (PMID 22179124, 2012). "In gliomas, GLUT1 is inhibited by miR-451, which targets the calcium-binding protein 39 (CAB39), thereby arresting glucose uptake and metabolism, as well as lactate production." (PMID 35348905, 2022). "In glioma cells, the effects of miR-451 are mediated by LKB1 in the AMPK pathway, where LKB1 is repressed by targeting CAB39." (PMID 25237911, 2014). "The levels of CAB39 increased markedly in high grade gliomas (WHO grades III and IV) in comparison to low grade gliomas (WHO grades I and II)." (PMID 22179124, 2012). "Furthermore, it promotes cancer cell metastasis via miR-451 and suppresses glioma cell proliferation and invasion in vitro and in vivo via suppression of the mTOR/HIF−1α/VEGF signaling pathway by targeting CAB39." (PMID 37511481, 2023). "In glioma cells, miR451a regulates liver kinase B1 (LKB1)/5′ adenosine monophosphate-activated protein (AMPK) signaling pathway by targeting CAB39 (MO25α) responding to cellular metabolic stress and indirectly inhibiting phosphatidylinositol 3-kinase (PI3K)/AKT pathway." (PMID 25237911, 2014). "Similar to glioma cell lines, our melanoma cells did exhibit a glucose-sensitive decreased cell migration; however, this action was not mediated by CAB39, suggesting the context-dependent action of miRNAs in gene regulation." (PMID 25237911, 2014).
colorectal cancer (5 papers, 2018 to 2024). A primary or metastatic malignant neoplasm that affects the colon or rectum. "We found that CAB39 was significantly downregulated in colorectal cancer tissues compared with that in normal tissues, which was consistent with our previous conclusion." (PMID 31919406, 2020). "We further narrowed this list by filtering genes with a known role in human colorectal cancer and/or cellular response to ionizing radiation that resulted in a group of four genes -CAB39, EMSY, EREG, and MEX3C." (PMID 29720118, 2018). "Similarly, CAB39 has been found as a target of miR-107 in both osteoblasts and colorectal cancer cells." (PMID 35317077, 2022). "We identified ELOF1and CAB39 as novel nuclear β-catenin accumulation regulatorsand devised a novel sorting strategy that could be leveraged to target APC-mutant colorectal cancer." (PMID 36589880, 2022). "Indeed, consistent with the breast cancer dataset, our analysis of the TCGA colorectal cancer dataset indicates that EMSY as well as CAB39 are increased at the protein level in a subset of patients and associated with worse outcome." (PMID 29720118, 2018). "Finally, analysis of a TCGA colorectal cancer dataset revealed that CAB39 and EMSY are upregulated at the protein level in a significant number of CRC patients." (PMID 29720118, 2018). "Moreover, analysis of the TCGA database (Provisional colorectal carcinoma, n = 633 patients) showed that CAB39 and EMSY protein levels were found to be upregulated in 14 and 6% of cases, respectively." (PMID 29720118, 2018). "Taken together, our data indicates miR-451a is induced by radiation and may influence colorectal carcinoma proliferation via CAB39 and EMSY pathways." (PMID 29720118, 2018). "On the other hand, miR-107-mediated suppression of CAB39 and subsequent activation of AMPK/mTOR signaling confers chemoresistance to colorectal cancer." (PMID 35317077, 2022). "Using a bioinformatics approach, we narrowed down the targets of miR-451a to a group of 14 genes, which was further filtered to 4 genes –CAB39, EMSY, EREG and MEX3C based on either a known role in colorectal cancer or radiation responsiveness in other cancer types." (PMID 29720118, 2018).
gastric cancer (5 papers, 2019 to 2024). A primary or metastatic malignant neoplasm involving the stomach. "For instance, miR-1265 can regulate cell proliferation and apoptosis in gastric cancer cells by targeting CAB39." (PMID 35317077, 2022). "CAB39 can activate the downstream AMPK-mTOR or ERK signaling pathway to promote the development of gastric cancer (GC) or HCC." (PMID 33262952, 2020).
hypertrophic cardiomyopathy (3 papers, 2012 to 2022). A condition in which the myocardium is hypertrophied without an obvious cause. "In transgenic mice with the α-MHC mutation R403Q, miR-195 upregulation and subsequent repression of Cab39 in the heart leads to hypertrophic cardiomyopathy owing to inhibition of Lkb1/Strad/Cab39-dependent AMPK signaling." (PMID 25364765, 2014).
Pancreatic Cancer (3 papers, 2019 to 2022). "CAB39 is a calcium-binding protein that is implicatedin hepatocellular and pancreatic carcinoma." (PMID 36589880, 2022). "The master regulator CAB39, previously identified as MO25, regulates protein kinases, and has been identified to be involved in cellular invasion and in both hepatic and pancreatic cancers." (PMID 31766405, 2019).
bladder cancer (2 papers, 2024 to 2025). "In CDDP-resistant bladder cancer cells, the calcium-binding protein-39 (CAB39) gene is overexpressed and linked to CDDP resistance." (PMID 39596278, 2024).
lung carcinoma (2 papers, 2022 to 2025). "For instance, the inhibitory impact of miR-451 on CAB39 has been shown to be implicated in drug-associated cardiac toxicity as well as lung cancer." (PMID 35317077, 2022). "HPV16 E6/E7 via the PI3K/AKT pathway by relieving miR-451 inhibitory effect on CAB39 could promote glucose uptake of GLUT1 in lung cancer cells." (PMID 35317077, 2022). "As there is still a lack of evidence of CAB39 on lung cancer, further in-depth studies are needed." (PMID 39949782, 2025).
melanoma (2 papers, 2014 to 2021). A malignant, usually aggressive tumor composed of atypical, neoplastic melanocytes. "Thus, expressing miR-144/miR-451a led to a more efficient processing and much higher levels of miR-451a.1, suggesting that this abundant isomiR, not miR-451a, inhibited melanoma cell migration and invasion, not mediated by CAB39." (PMID 25237911, 2014).
Autoimmunity (1 paper, 2025). The occurrence of an immune reaction against the organism's own cells or tissues. "Conversely, the AD-A group demonstrated upregulation of several transcripts implicated in tumorigenesis (CAB39), intracellular signaling (CAB39), autoimmunity (IFIT3), and mTOR signaling (DEPTOR)." (PMID 41010010, 2025).
breast tumors (1 paper, 2018). "Furthermore, the expression of both Cab39 (P = 2.734 × 10–14) and Prkaa2 (AMPK catalytic alpha subunit; P = 1.442 × 10–7) is lower in breast tumors of African-Americans compared with whites." (PMID 30165877, 2018).
diabetes (1 paper, 2025). "Although Cab39 has been reported to act as a key downstream effector of miR-451, in our study we did not perform rescuing experiments demonstrating the causal contribution of this protein to rescuing diabetes-induced lipotoxic injury." (PMID 40940812, 2025). "Targeting miR-451 led to restoration of Cab39 levels while rescuing diabetes-induced lipotoxic injury and metabolic dysfunction." (PMID 40940812, 2025). "Of interest, an increase in the endogenous miR-451 levels in cultured human cardiomyocytes led to Cab39 downregulation while recapitulating features of diabetes-induced lipotoxic injury, namely TG accumulation, oxidative stress, apoptosis and mitochondrial disruption." (PMID 40940812, 2025). "We next validated the Cab39 expression in our setting and found a significant downregulation of Cab39 in myocardial specimens from the T2D patients vs. the controls without diabetes." (PMID 40940812, 2025). "However, previous work has shown a strong concordance between the gene and protein expression levels of Cab39 and AMPK in experimental models of diabetes." (PMID 40940812, 2025).
glioblastoma (1 paper, 2021). The most malignant astrocytic tumor (WHO grade IV). "Studies in Glioblastoma cellular proliferation and migration for both of these proteins identified the potential of therapeutically targeting miR-451 in order to inhibit cell growth and slow down cell migration through the blocking of the CAB39/AMPK pathway." (PMID 34199766, 2021).
Hyperglycemia (1 paper, 2025). An increased concentration of glucose in the blood. "Of note, targeting miR-451 in human CMs exposed to hyperglycemia and palmitic acid restored the Cab39 levels and prevented TG accumulation and lipotoxic injury as assessed by the levels of oxidative stress, mitochondrial dysfunction and apoptosis." (PMID 40940812, 2025).
infarction (1 paper, 2020). A localised pathological necrosis of tissue resulting from obstruction of the blood supply usually by a thrombus, an embolus, or vascular torsion. "In summary, our study demonstrates that inhibition of miR‐155‐5p, partially via the Cab39/AMPK signaling pathway, rejuvenates aged MSCs by regulating mitochondrial dynamics and provides a candidate target to enhance the cardioprotection of MSCs for the aged heart following infarction." (PMID 32196916, 2020).
liver cancer (1 paper, 2019). An epithelial or non-epithelial malignant neoplasm that arises from the liver. "By screening the Human Protein Atlas database, we also found that liver cancer patients with lower expression levels of IL1β and Cab39 had higher survival rates." (PMID 31816816, 2019). "In addition, the Human Protein Atlas database showed that liver cancer patients with high expressions of IL1β and Cab39 had lower survival rates." (PMID 31816816, 2019). "In the liver cancer cell line (HepG2), genistein significantly promoted miR-451 expression, and both the miR-451 mimic and genistein significantly inhibited the expression of IL1β and Cab39." (PMID 31816816, 2019). "MiR-451 and its target genes, IL1β and Cab39, may play an important role in the mechanism by which genistein inhibits NAFLD/NASH and liver cancer." (PMID 31816816, 2019).
osteoarthritis (1 paper, 2022). A noninflammatory degenerative joint disease occurring chiefly in older persons, characterized by degeneration of the articular cartilage, hypertrophy of bone at the margins and changes in the synovial membrane. "In this study, we sought to study the impact of CAB39 on the macrophage polarization and the effect of activated macrophage on chondrocyte damage in osteoarthritis." (PMID 35412939, 2022).
paroxysmal AF (1 paper, 2023). "Furthermore, CAB39 and its binding partners LKB1 (liver kinase-B1) and STRAD (LYK5) are downregulated in human atrial biopsies in patients with paroxysmal AF." (PMID 36831306, 2023).
periodontitis (1 paper, 2025). An acute or chronic inflammatory process that affects the tissues that surround and support the teeth. "Our results showed that DNMT3B was significantly negatively correlated with GRASP, HLA-DMB, HLA-DMA, CAB39, and TLE4, implying the predominant role of DNMT3B in periodontitis." (PMID 40267082, 2025). "After integrating DNA methylation with transcriptome profiles, GRASP, HLA-DMB, HLA-DMA, CAB39, NCOA2 and TLE4 were identified as candidate genes in periodontitis PMNs." (PMID 40267082, 2025).
rectal cancer (1 paper, 2018). A primary or metastatic malignant neoplasm that affects the rectum. "Importantly, we found miR-451a expression was high and CAB39, EMSY levels were low in a small subset of rectal cancer patients who had a partial response to chemoradiation when compared to patients that had no response." (PMID 29720118, 2018).
renal fibrosis (1 paper, 2020). A final common manifestation of a wide variety of chronic kidney diseases characterized by glomerulosclerosis and tubulointerstitial fibrosis. "Mir-181a-5p has been found to downregulate lipid metabolism regulator PPARα and is in silico predicted to downregulate MAT2A, TIMP3, and LGSF11; miR-451 downregulates YWHAZ and CAB39, which could be implicated in renal fibrosis and mesangial hypertrophy." (PMID 32849923, 2020).
Sepsis (1 paper, 2021). Sepsis is defined as life-threatening organ dysfunction caused by a dysregulated host response to infection. "The adenosine monophosphate-activated protein kinase pathway, which is extensively involved in cellular energy homeostasis, was also upregulated and associated with three co-expressed mRNAs (CAB39, PFKFB3, and PRKAA1) in sepsis." (PMID 34907156, 2021).
tumor (15 papers, 2016 to 2025). "Our study showed that CAB39 was upregulated after DCA treatment, and CAB39 inhibition was associated with tumour cell resistance to L-OHP, suggesting that CAB39 plays an important role in regulating the chemoresistance of CRC." (PMID 31919406, 2020). "In contrast, miRNA-451 can promote cell proliferation and metastasis in PDAC by down-regulating CAB39 (Calcium binding protein 39), a tumor suppressor upstream of STK11 (serine-threonine kinase 11)." (PMID 34368146, 2021). "In addition to having a role in metabolism, cell polarity, autophagy, and tumour progression, CAB39 is also recognised as an oncogenic factor." (PMID 36590595, 2022). "Moreover, we found that CAB39 expression was lower in tumour tissues than in adjacent tissues, indicating that CAB39 acts as a tumour suppressor in CRC." (PMID 31919406, 2020). "Finally, the expression of CAB39 was identified as anatomic site-specific signature of “infiltrating tumor”." (PMID 30875963, 2019). "Among them, the expression of TIPRAP, WSCD1, TCP11L2, DPP4, CAB39 and PDPK1 were down-regulated, while PARP1, DEPDC1B, CKAP2, ORMDL2, MRPL44, POLD4 and TMEM187 were increased in tumor group." (PMID 39949782, 2025). "Expression of calcium-binding protein 39 in human HCC tissue was found to be elevated compared to that in non-tumor liver tissue and higher levels of expression correlated with tumor metastasis and poor survival." (PMID 32987945, 2020). "CAB39, a paralog of CAB39L, has been reported to interact with LKB1 and STE20-Related Kinase Adaptor (STRAD), leading to activation of LKB1, a bona fide tumor suppressor and an upstream kinase that phosphorylates AMPK." (PMID 30054562, 2018). "Recent studies have shown that miR-451 regulates downstream molecules including AMPK/CAB39/MARK and mTOR to determine the balance between rapid proliferation and invasion in response to metabolic stress in the harsh tumor microenvironment." (PMID 30286133, 2018). "Additionally, in LUAD, TCP11L2 was the only protein decreased in the tumor samples, and in LUSC, CAB39, DEPDC1B, DPP4, PDPK1, and POLD4 were significantly down-regulated." (PMID 39949782, 2025). "In summary, these results confirm that miR-1265 acts as a tumor suppressor in HCC, and circGSK3B may positively regulate the ceRNA target CAB39 through miR-1265, thereby promoting HCC progression." (PMID 33262952, 2020).
cancer (12 papers, 2018 to 2025). A tumor composed of atypical neoplastic, often pleomorphic cells that invade other tissues. "Taken together, circGSK3B/miR-1265/CAB39 axis has a role in enhancing proliferation, migration, invasion of this kind of cancer." (PMID 35317077, 2022). "Its overexpression causes the calcium binding Protein 39 / Liver kinase B1/AMP-activated protein kinase (CAB39/LKB1/AMPK) pathway to be repressed, which enhances the rate of cancer cell proliferation." (PMID 35716231, 2022). "The interaction between miRNAs and CAB39 has an important role in the pathogenesis of cancers." (PMID 35317077, 2022). "Based on the results of our study, and in view of the ability of genistein to regulate the expression of miR-451, IL1β, and Cab39, we speculate that miR-451 and its target genes are also involved in the anti-cancer effects of genistein." (PMID 31816816, 2019). "CAB39, a component of a trimeric complex including serine/threonine kinase 11 (STK11) and STE20-related adaptor alpha (STRAD), has been studied in the context of cancer progression, but with unknown function during SARS-CoV-2 infection." (PMID 40833112, 2025).
adenocarcinoma (1 paper, 2020). A common cancer characterized by the presence of malignant glandular cells. "Using the Oncomine database, we also found that the expression of CAB39 was significantly higher in normal epithelium tissues than in adenocarcinoma tissues." (PMID 31919406, 2020).
infection (1 paper, 2020). The state of being infected such as from the introduction of a foreign agent such as serum, vaccine, antigenic substance or organism. "Forced overexpression of miR-107, by infection of pre-miR-107 lentivirus or transfection of wild-type miR-107 mimic, largely inhibited CAB39 expression in OB-6 cells and primary human osteoblasts." (PMID 32527986, 2020). "In the primary human osteoblasts, infection of LV-pre-miR-107 resulted in miR-107 overexpression, but CAB39 mRNA and protein downregulation." (PMID 32527986, 2020). "Forced overexpression of miR-107, by infection of LV-pre-miR-107 or transfection of the wild-type miR-107 mimic, largely inhibited CAB39 3’-UTR luciferase activity and its expression in OB-6 cells and primary human osteoblasts." (PMID 32527986, 2020).
CAB39 also shares sentences with these, for which no sentence is quoted: cardiac hypertrophy (4 papers); hepatocellular carcinoma (2); acute lung injury (1); breast carcinoma (1); heart failure (1); Insulin resistance (1); ischemic stroke (1); muscular dystrophy (1); myocardial infarction (1); Neurological Disorder (1).